HMOX1 (heme oxygenase 1)
Diseases named in the same sentence as HMOX1 in open-access papers (continued):
Sharing a sentence is not in itself a finding about the gene and the disease.
breast carcinoma (continued). "Recently, it has been shown that ATF4 stimulates expression of LAMP3 in facilitating breast cancer cell migration and directly transactivates HO-1 (heme oxygenase 1) gene expression to inhibit anoikis and to promote tumor metastasis." (PMID 31064130, 2019). "Further, macrophage-specific suppression of heme oxygenase 1 (HMOX1), an iron-releasing enzyme, correlated with reduced tumor growth in breast carcinoma and prostate cancer models, an effect attributed to activation of an M1 profile in TAMs." (PMID 31535086, 2019). "Taken together, our experiments suggest that NFκB family members and HMOX-1 interact on a gene level, when breast cancer cells transit from a 2D to a 3D growth on the RPM." (PMID 29343717, 2018). "HMOX1, highly induced under oxidative stress, was shown to exert antiproliferative and proapoptotic effects on some rat and human breast cancer cell lines." (PMID 29202775, 2017). "According to some studies that investigate the antioxidant and anti-inflammatory effect of statins, atorvastatin activates heme oxygenase-1 at the stress response elements in prostatic cancer cells and breast cancer cells." (PMID 27323826, 2016). "In breast cancer, 17 genes were associated with poor prognosis, such as glucose-6-phosphate dehydrogenase (G6PD), heme oxygenase (decycling) 1 (HMOX1) and thioredoxin reductase 1 (TXNRD1), and only 2 with good outcome." (PMID 24342878, 2013). "We demonstrate that high HMOX1 and low CD8A expression in breast cancer is associated with poorer outcomes, suggesting that these patients may benefit from HO inhibition to overcome immunosuppression in the TME." (PMID 40627458, 2025). "Here, we show that upregulation of DNAJB1 and HMOX1 in MCF7 breast cancer cells was time-dependent." (PMID 39138277, 2024). "Hemin-induced heme oxygenase-1 (HO-1) in breast cancer cells is slightly inhibited by brazilin." (PMID 38515856, 2024). "Additionally, the Heme-Oxygenase 1 (HO-1) is up-regulated at a protein level by TChal, and this is able to reduce breast cancer in xenograft assays with nude mice." (PMID 37445965, 2023). "Hence, we examined the xenobiotic metabolism-associated genes (PYCR1, KYNU, CFB, HMOX1 and HES6) expressed in both breast cancer cells and in normal mammary epithelial cells." (PMID 37845207, 2023). "Moreover, it significantly induced antioxidant signaling proteins such as Nrf2 and Heme oxygenase 1 (HO-1) in the MCF-7 breast cancer cell line." (PMID 36289931, 2022). "BAY11–7085 induced ferroptosis of breast cancer cells by upregulating HMOX1." (PMID 36536381, 2022). "Additionally, 15-Delta prostaglandin J2 can suppress NF-κB and AP-1-mediated MMP-9 expression, and invasion of breast cancer cell by means of a heme oxygenase-1-dependent mechanism." (PMID 33796449, 2021). "Moreover, high expression of all three genes (PTGS2, NFE2L2, and HMOX1) correlated with poor prognosis in breast cancer patients." (PMID 33801351, 2021). "In addition, a study has shown that inhibition of heme oxygenase 1 (HO-1; which is an enzyme that degrades heme to release iron) in TAMs induced M1 polarization in macrophages and reduced tumor growth in a breast cancer mouse model." (PMID 32509781, 2020). "Reduction of MMP-9 expression by HMOX1 was also observed in breast cancer cells." (PMID 27829220, 2016).
breast carcinoma (continued). "Analysis of mammary tumor interstitial fluid compared to matching plasma revealed that the heme metabolite bilirubin was elevated intratumorally, which could be partially reversed via Hmox1 knockdown." (PMID 42106562, 2026). "Indeed, curcumin could activate ferroptosis in breast cancer cells, and HMOX1 could promote curcumin-induced ferroptosis." (PMID 36838613, 2023). "Hence, the elucidation of HMOX1 in breast cancer metastasis needs to be further investigated." (PMID 35154262, 2021). "Conversely, Heme Oxygenase-1 may inhibit lung metastases in a murine breast cancer model." (PMID 34988012, 2021). "Specifically, in breast cancer cells with high Fe2+ concentrations, protein arginine methyltransferase 5 targets the NRF2/heme oxygenase 1 (HMOX1) axis and slows down the ferrous import." (PMID 39935430, 2025). "This was attributed to the ability of fasting/FMD to reduce the Treg population and boost CD8 infiltration by downregulating the expression of heme oxygenase-1 (HO-1) and IGF-1 and by inducing autophagy in melanoma and breast cancer." (PMID 37568713, 2023). "Another study has shown that curcumin induces heme oxygenase-1 protein levels and Nrf2 in a dose-dependent manner in HBL100 and MDA-MB-468 breast cancer cell lines." (PMID 35126099, 2021). "In our experimental setting on breast cancer cells grown on the RPM, HMOX-1 was upregulated, while NFKB3 remained unregulated." (PMID 29343717, 2018). "Here we showed that let-7a overexpression induced HMOX1 and repressed BACH1 also in breast cancer and melanoma cell lines." (PMID 25669981, 2015). "Microarray analysis in breast cancer cells revealed that knockdown of MTDH led to decreased expression of chemoresistance genes ALDH3A1, MET, HSP90, and HMOX1 and increased expression of proapoptotic genes BNIP3 and TRAIL." (PMID 25993398, 2015). "Notably, RNA-Seq analysis revealed that AdipoR1 stimulation upregulated ferroptosis-related genes, DDIT3, HMOX1, and IRE1α, and downregulated proliferation-related genes, estrogen receptor and TROP2, in breast cancer cell lines." (PMID 41888104, 2026). "Consistently, the real-time PCR analysis confirmed that 4HC treatment led to a significant increase in Hmox-1 and Slc7a11 mRNA levels at an early stage (within 6 h) in the murine glioblastoma cell lines GL261, CT-2A, and KR-158 and the 4T1 murine breast cancer." (PMID 35264971, 2022). "HMOX1 inhibitors enhance the anti-tumor effects of anti-PD-L1 antibodies in mouse melanoma and also reduce tumor size by abolishing resistance to anti-PD1 immunotherapy in female mice bearing E0771 mammary tumors." (PMID 36189226, 2022). "Moreover, patients with breast cancer exhibited higher ISR after chemotherapy, and the elevated mRNA levels of HMOX1, SHMT2 and EIF2A were correlated with poor prognosis." (PMID 31211507, 2019). "In addition, analyses of publicly available data sets revealed that the mRNA levels of the ISR‐related antioxidant genes, HMOX1 and SHMT2, negatively correlated with relapse‐free survival of breast cancer patients." (PMID 31211507, 2019). "We addressed this objective by assessing in the DS-exposed luminal breast cancer cells the expression of key regulators of these processes, including B-cell lymphoma-2 (BCL-2)-related protein A1(BCL-2A1), cellular FLICE-inhibitory protein (cFLIP), Beclin1, and heme oxygenase-1 (HO-1)." (PMID 41148796, 2025). "The patented traditional Chinese medicine, Shuganning injection, could selectively upregulate heme oxygenase 1 (HO-1) expression in TNBC cells, leading to lipid iron pool accumulation and ferroptosis occurrence, inhibiting breast cancer tissue growth both in vivo and in vitro." (PMID 39664391, 2024).
atherosclerosis (169 papers, 2008 to 2026). A disease characterized by the build-up of fatty material and calcium deposition in the arterial wall resulting in partial or complete occlusion of the arterial lumen. "Taken together, our present study suggested HMOX1 as a potential diagnostic biomarker for atherosclerosis and provided more evidence about the vital role of ferroptosis in atherosclerosis progression." (PMID 35498043, 2022). "Our results suggested HMOX1 as a potential diagnostic biomarker for atherosclerosis, providing more evidence about the important role of ferroptosis in atherosclerosis progression." (PMID 35498043, 2022). "One of them is heme oxygenase-1 (HO-1), whose expression has a protective effect on vascular and nerve damage caused by atherosclerosis and ischemia-reperfusion injury." (PMID 35463081, 2022). "Their vital role in the homeostasis of NO was adopted for designing one of the mouse models of atherosclerosis development by knocking out the gene of the enzyme that participates in NO production (human HO-1 deficiency and Hmox1 −/− mice)." (PMID 35887276, 2022). "The deficiency of glutathione peroxidase (Gpx)-1 exacerbates atherosclerosis and loss of heme oxygenase-1 (HO-1) accelerates the development of atherosclerosis and vascular remodeling in ApoE‒/‒ mice." (PMID 34439492, 2021). "Antioxidant defenses reported to be associated with atherosclerosis include the activation of nuclear erythroid factor 2–related factor 2 (Nrf2)/Heme Oxygenase-1 (HO-1) pathway." (PMID 34943105, 2021). "In response to oxidative stress stimuli, cells implement several defense mechanisms and, among them, the activation of nuclear erythroid factor 2 – related factor 2 (Nrf2)/heme oxygenase-1 (HO-1) pathway was reported to be associated with atherosclerosis." (PMID 30995787, 2019). "Hypercholesterolemic mice, deficient in both HMOX1 and ApoE (HMOX1−/−/ApoE−/−), demonstrated enhanced development of atherosclerosis compared to ApoE−/− single knockout mice." (PMID 29104732, 2017). "Additionally, Nrf2 and its representative downstream target heme oxygenase-1 (HO-1) have been implicated in macrophages’ phenotypes and atherosclerosis." (PMID 37432260, 2023). "In light of the severe vascular endothelial injury and accelerated atherosclerosis reported in HMOX1 deficiency, we believe that this pathway is worthy of further study as an important contributor to endothelial homeostasis and resistance to endothelial injury." (PMID 25883219, 2015). "The research findings revealed that HMOX1 is prominently expressed in atherosclerotic plaques and acts as an autophagy regulator, holding a pivotal modulatory role in atherosclerosis." (PMID 41031220, 2025). "Mechanistically, HM13/SPP enhances foamy macrophage formation and atherosclerosis via promoting ERAD‐mediated proteasomal degradation of the metabolic regulator Heme Oxygenase‐1 (HO‐1)." (PMID 40112173, 2025). "Among the genes implicated in atherosclerosis‐related ferroptosis, HMOX1, encoding HO‐1, has been identified as a critical pro‐ferroptotic gene." (PMID 38873710, 2024). "We then discuss divergent beneficial and pathological roles for HMOX1 in disorders such as atherosclerosis and metabolic syndrome, where activation of the HMOX system sits at the crossroads of chronic low-grade inflammation and oxidative stress." (PMID 38585264, 2024). "In the study of ferroptosis-related differentially expressed genes of atherosclerosis, HMOX1 was found to be remarkably increased and its inhibitor protected HASMCs from erastin-induced ferroptosis." (PMID 37415103, 2023). "Both heme-oxygenase 1 and ferritin were also expressed in erythrocyte-rich regions of carotid plaques from ApoE−/−Fbn1C1039G+/− mice, a model of advanced atherosclerosis with IP angiogenesis." (PMID 37120604, 2023). "Heme oxygenase-1 (HO-1) has been reported to protect against oxidation and inflammation in atherosclerosis." (PMID 35281895, 2022).
atherosclerosis (continued). "Intriguingly, in ApoE-KO mice with Hmox1 deletion, the atherosclerosis and oxidative stress were accelerated." (PMID 35204118, 2022). "HMOX1 has been shown to reduce atherosclerosis in mouse models, and upregulation of Nrf2/HMOX1 protected the human endothelial cells against TNF-α activation." (PMID 36359349, 2022). "Both datasets identified HMOX1 as a key FRG which remarkably increased as atherosclerosis progressed." (PMID 35498043, 2022). "Since HMOX1 was identified as a pro-ferroptotic gene in atherosclerosis, it would be interesting to confirm the possible relationship between ferroptosis of VSMCs and MMPs producing." (PMID 35498043, 2022). "Our previous study indicated that SDT inhibits early stage atherosclerosis progression and upregulates heme oxygenase‐1 (HO‐1) levels." (PMID 33532592, 2021). "The NF-E2–related factor 2 (Nrf2)/Heme Oxygenase-1 (HO-1) pathway has an emerging role in atherosclerosis." (PMID 34943105, 2021). "In contrast, the genetic ablation of Hmox1 in apolipoprotein E-knockout mice accelerated the development of atherosclerosis and exacerbated lesion formation." (PMID 31344980, 2019). "Deficiency of the heme-catabolizing enzyme, heme oxygenase-1 (HO-1), in humans was found to be associated with elevated plasma heme levels, extensive LDL oxidation, severe endothelial damage and accelerated atherosclerosis." (PMID 25324785, 2014). "Increases in Nrf2 expression at this stage of atherosclerosis development is significant because of downstream effects on heme oxygenase-1 (HO-1), which produces antiatherogenic reductions foam cell formation." (PMID 23691261, 2013). "The results of network pharmacology analysis also suggest that the two antioxidant‐related genes, NFEL2 and HMOX1, may play vital roles in the process of GE improving atherosclerosis." (PMID 40718724, 2025). "CYBB, HMOX1, IL1B, TYROBP, and CSF1R are key genes associated with ferroptosis, a form of cell death triggered by lipid metabolism abnormalities in the context of atherosclerosis." (PMID 40895546, 2025). "Heme oxygenase-1 (HMOX1) is a key regulatory gene of ferroptosis in atherosclerosis." (PMID 40697914, 2025). "The various antioxidant, anti‐inflammatory, and endothelial protective effects of HMOX‐1 may limit the progression of atherosclerosis as shown in models of disease." (PMID 38958135, 2024). "Studies have shown that PCB can reverse CCl4 induced liver injury in mice through anti-inflammatory ability, prevent diabetes nephropathy, protect nerves, improve ischaemic stroke (IS) by inhibiting oxidative stress, and cure atherosclerosis by activating HMOX1." (PMID 35726224, 2022). "In conclusion, we identified HMOX1 as an essential pro-ferroptotic gene in VSMCs, and demonstrated that high expression of HMOX1 in atherosclerosis might indicate the occurrence of ferroptosis, resulting in MMPs releasing and M0 macrophages infiltration." (PMID 35498043, 2022). "Although OxPLs have some protective effects, such as the activation of prostaglandin E2 production and heme oxygenase 1 (HO-1) formation, OxPLs strongly accumulate under high concentrations of atherosclerotic lesions, which led us to conclude that the OxPL molecule is an atherosclerosis promotor." (PMID 32099678, 2020). "Thus, crossing Hmox1−/− mice with atherosclerosis prone ApoE-/- animals resulted in more extensive and complex plaques, while HO-1 induction impeded atherogenesis and stabilized plaques." (PMID 25883219, 2015). "Furthermore, the protective role of heme oxygenase-1 (HO-1) in atherosclerosis is also attributed to its induction of p21." (PMID 19604372, 2009).
atherosclerosis (continued). "We then assessed HMOX1 mRNA expression levels in the two GEO datasets and found significantly higher HMOX1 expression levels in advanced atherosclerotic plaques than early atherosclerotic plaques, as well as higher in atherosclerosis tissues compared to normal tissues." (PMID 35498043, 2022). "In the future study, administration of hemin, erastin, DOX, or other ferroptosis inducers in HMOX1−/− mice may not only provide in vivo evidence supporting the pro-ferroptotic role of HMOX1, but also help to explore the implication of ferroptosis at various stages of atherosclerosis." (PMID 35498043, 2022). "Nrf2-regulated genes such as heme oxygenase (decycling) 1 (HMOX1), peroxiredoxin (PRDX1), glutathione peroxidase 1 (GPX1), glutamate-cysteine ligase modifier subunit (GCLM) and NADPH quinine oxidoreductase 1 (NQO1) have been implicated in the protection against atherosclerosis and oxidative stress." (PMID 29113088, 2017). "Heme oxygenase-1 expression in endothelial cells could also play a role in the protection against atherosclerosis induced by environmental factors such as smoking and exposure to air pollution, which has been shown to lead to increased atherosclerosis in several animal models." (PMID 22833723, 2012). "The shortest way in CTPDN mainly divided into three types, AKT1, lipid and atherosclerosis, CAT and chemical carcinogenesis—receptor activation, and AKT1 or HMOX1 with STAT1 together acting on fluid shear stress and atherosclerosis." (PMID 40217538, 2025). "In conclusion, this study found that the important direct targets of hawthorn in atherosclerosis included IL1B, CTSD, HMOX1, and PPARG." (PMID 40824771, 2025). "In a similar manner to human atherosclerosis, BLVRB and its upstream enzyme in Hb catabolism, HMOX1, were also expressed in regions of CD68-positive macrophages in atherosclerotic mouse vein grafts." (PMID 37371462, 2023). "We divided advanced atherosclerosis samples of GSE28829 and all atherosclerosis samples of GSE43292 into HMOX1 high-expression group and HMOX1 low-expression group and filtered out the 40 most significant DEGs separately." (PMID 35498043, 2022). "HMOX1, found in both of the two Venn diagrams, was recognized as an important FRG to regulate ferroptosis in atherosclerosis." (PMID 35498043, 2022). "With a particular focus on atherosclerosis imaging, we highlight recent approaches to report on the activity of cathepsins (K and B), matrix metalloproteinases (MMP-2 and MMP-9), thrombin, heme oxygenase-1 (HO-1) and myeloperoxidase (MPO)." (PMID 34605500, 2021). "KTRI for hawthorns in the PVAT microenvironment of atherosclerosis were CTSD, PPARG, and HMOX1." (PMID 40824771, 2025). "KTRI for hawthorn in the PVAT microenvironment of atherosclerosis were CTSD, PPARG, and Hmox1." (PMID 40824771, 2025). "The appearance of the keywords “heme oxygenase 1” and “blood stasis syndrome” may suggest the application of Traditional Chinese Medicine (TCM) theories in this field, such as treating atherosclerosis by improving blood stasis syndrome." (PMID 38952541, 2024). "Despite the antioxidant function of Nrf2 and the antiatherogenic function of the key Nrf2 target gene HMOX1, the global knockout of Nrf2 (Nrf2−/−) developed less rather than more atherosclerosis." (PMID 29104732, 2017). "Consistent with this hypothesis, the Nrf2-regulated gene, heme oxygenase 1 (HMOX1), demonstrates significant cytoprotective and anti-inflammatory effects that result in a reduction of atherosclerosis in mouse models, possibly through production of low levels of carbon monoxide." (PMID 29104732, 2017). "KEGG pathway enrichment of DEGs demonstrated that high expression of HMOX1 might have connections with cholesterol metabolism, phagosome, PPAR signaling pathway, TNF signaling pathway, and renin-angiotensin system, most of which were activated through the development of atherosclerosis." (PMID 35498043, 2022).
atherosclerosis (continued). "Interestingly, a case study of a HMOX1-deficient patient demonstrated that the absence of the enzyme triggered endothelial damage, high plasma levels of von Willebrand factor, increased ICAM-1 expression, coagulation and fibrinolysis defects, generalized inflammation and premature atherosclerosis." (PMID 32611348, 2020).